CHD7 (chromodomain helicase DNA binding protein 7)
Description:
ATP-dependent chromatin-remodeling factor, slides nucleosomes along DNA; nucleosome sliding requires ATP. Probable transcription regulator. May be involved in the in 45S precursor rRNA production.
Synonyms: KIAA1416; FLJ20357; FLJ20361; CRG; HH5; IS3; KAL5
Tractability: PROTAC: ubiquitination databases record sites on it.
Gene: Protein-coding gene on chromosome 8 (60,678,740 to 60,868,028, forward strand). Ensembl gene ENSG00000171316.
Subcellular location: Nucleus (Isoform 1); Nucleus, nucleolus (Isoform 3)
Subcellular location (Human Protein Atlas): Nucleoplasm; Nucleoli
Pathways (Reactome):
Chromatin organization: CHD6, CHD7, CHD8, CHD9 subfamily
Gene Ontology:
Molecular function: ATP hydrolysis activity; protein binding; ATP-dependent chromatin remodeler activity; chromatin binding; DNA binding; histone binding; ATP binding; promoter-specific chromatin binding; RNA polymerase II cis-regulatory region sequence-specific DNA binding
Biological process: central nervous system development; cognition; cranial nerve development; face development; genitalia development; heart morphogenesis; in utero embryonic development; inner ear morphogenesis; limb development; nose development; regulation of growth hormone secretion; retina development in camera-type eye; secondary palate development; skeletal system development; T cell differentiation; chordate embryonic development; chromatin remodeling; regulation of DNA-templated transcription; regulation of gene expression; camera-type eye development; head development; nervous system process; regulation of transport; roof of mouth development
Cellular component: nucleolus; nucleoplasm; nucleus; chromatin
Genetic constraint (gnomAD): Loss-of-function variants: 21 observed, 277.9 expected, observed/expected ratio (o/e) 0.0756, 90% interval 0.053 to 0.11. The upper end of that interval is the gene's LOEUF score, 0.11, which puts it in group 1 of 6, group 1 being the genes least tolerant of losing a copy. Missense variants: 3,045 observed, 3,705.1 expected, observed/expected ratio (o/e) 0.82, 90% interval 0.8 to 0.85. Synonymous variants: 1,337 observed, 1,356.3 expected, observed/expected ratio (o/e) 0.99, 90% interval 0.94 to 1.03.
Gene-disease validity (ClinGen):
ClinGen rates the evidence that CHD7 causes each of these diseases.
CHARGE syndrome (autosomal dominant): Definitive. CHARGE syndrome is a multiple congenital anomaly syndrome characterized by the variable combination of multiple anomalies, mainly Coloboma; Choanal atresia/stenosis; Cranial nerve dysfunction; Characteristic ear anomalies (known as the major 4 C's).
Homologues: Orthologues: chimpanzee CHD7 (99% identical), macaque CHD7 (99% identical), rabbit CHD7 (98% identical), guinea pig CHD7 (96% identical), dog CHD7 (96% identical), mouse Chd7 (95% identical), rat Chd7 (95% identical), pig CHD7 (94% identical), tropical clawed frog chd8 (83% identical), zebrafish chd7 (66% identical). Paralogues in human: CHD9 (48% identical), CHD8 (43% identical), CHD6 (43% identical), CHD5 (15% identical), CHD3 (15% identical), CHD4 (15% identical), CHD2 (13% identical), CHD1 (13% identical), EP400 (12% identical), SMARCA2 (12% identical), SMARCA4 (12% identical), SRCAP (12% identical), and 18 more.
Diseases named in the same sentence as CHD7 in open-access papers:
CHD7 is named in the same sentence as 203 diseases in open-access papers, as found by Europe PMC text mining. Sharing a sentence is not in itself a finding about the gene and the disease. The quoted sentences say what the papers report.
CHARGE syndrome (280 papers, 2006 to 2026). "We report a Chilean female proband with genetically confirmed CHARGE syndrome caused by a pathogenic variant in the CHD7 gene, who presented with HI in the neonatal period." (PMID 41743177, 2026). "CHARGE syndrome (CS) is a congenital anomaly syndrome caused by a variant in the CHD7 gene, which is necessary for fetal development." (PMID 40954203, 2026). "De novo variants in chromodomain helicase DNA binding protein 7 (CHD7) cause 67% of CHARGE syndrome cases." (PMID 41664627, 2026). "The chromodomain helicase remodeling enzyme, CHD7, has been directly linked to CHARGE syndrome, however recent studies show a wide variability of pathways regulated by the chromatin remodeling enzyme." (PMID 42155613, 2026). "Defects and mutations in PUF60 or CHD7 have been identified in human congenital disorders, specifically Verheij syndrome and CHARGE syndrome." (PMID 41596295, 2026). "CHD7 is a DNA-binding chromatin remodeler with thousands of predicted binding sites in the genome, making it challenging to define molecular pathways linking loss of CHD7 to CHARGE syndrome phenotypes." (PMID 41664627, 2026). "This allowed for a targeted analysis of CHD7, which led to the identification of a CHD7 frameshift variant within 48 h and confirmed the diagnosis of CHARGE syndrome (MIM#214800)." (PMID 41116046, 2026). "Animal models, including zebrafish and mice, show that mutations in Chd7 recapitulate craniofacial and cardiovascular defects found in CHARGE syndrome." (PMID 39941150, 2025). "Several predicted pathogenic CHD7 variants have been identified in individuals with isolated features of CHARGE syndrome; therefore, this was also possible in our case." (PMID 40989825, 2025). "Morphologically, CHD7-deficient zebrafish effectively recapitulate human CHARGE syndrome phenotypes, demonstrating various physiological symptoms such as pericardial edema, cardiomegaly, small eyes, auditory deficits, and more." (PMID 40801603, 2025). "In individuals fulfilling the diagnostic criteria for CHARGE syndrome, CHD7 sequencing and targeted analyses directed to identify structural rearrangements involving the gene are expected to confirm the diagnosis in all cases." (PMID 40004505, 2025). "CHD7, located on chromosome 8, is responsible for CHARGE syndrome and was first discovered in a study that uncovered mutations in CHD7 in individuals with this disorder." (PMID 39941150, 2025). "For instance, Treacher Collins syndrome arises from mutations affecting ribosome biogenesis in neural crest progenitors, whereas CHARGE syndrome involves mutations in CHD7, a chromatin remodeler essential for NCCs specification." (PMID 40988739, 2025). "Our results implicate a general mechanism of CHD7 in facilitating neuronal differentiation and provide insight into CHD7 dysfunction in CHARGE syndrome, a congenital disorder associated with hearing loss." (PMID 40236205, 2025). "For example, variants in the CHD7 gene, primarily associated with CHARGE syndrome (OMIM #214800), have recently been found in patients with overlapping but distinct clinical features, widening the spectrum of CHD7-related disorders." (PMID 40620702, 2025). "CHARGE syndrome is a collection of congenital malformations resulting from pathogenic variants that cause loss of function in the CHD7 gene." (PMID 41210246, 2025). "Another chromatin remodeler, CHD7, also plays a crucial role in neural crest development, and its mutations cause the CHARGE syndrome." (PMID 39941150, 2025). "Retrieved knowledge enabled the exclusion of genetically distinct CHARGE syndrome (associated with CHD7 mutations)." (PMID 40849403, 2025). "Despite prior karyotyping, CMA, and even ES, a diagnosis remained elusive until GS revealed a heterozygous 0.3 kb deletion spanning Exons 30–31 of CHD7, associated with “CHARGE syndrome (OMIM: 214800)” that was suspected from the beginning." (PMID 40226308, 2025).
CHARGE syndrome (continued). "LOF variants in CHD7 cause CHARGE syndrome, featuring coloboma, atresia choanae, slow growth and development, genital malformations, ear malformations, and congenital heart disease (31, –33)." (PMID 40127276, 2025). "Cochlear hypo/aplasia and colobomatous microphthalmia are common findings in CHARGE syndrome, which is caused by heterozygous mutations in the chromodomain helicase DNA-binding protein 7 (CHD7) gene encoding a chromatin remodeler." (PMID 40004505, 2025). "We present a case of CHARGE syndrome in a newborn with esophageal atresia and feeding difficulties as the main manifestations, which was confirmed by genetic analysis demonstrating CHD7 mutation." (PMID 41210246, 2025). "Intriguingly, an intronic de novo variant in CHD7 was observed in a TOF proband who had phenotypic features consistent with CHARGE syndrome which is caused by CHD7 variants." (PMID 39402625, 2024). "In the Chinese population with CHARGE syndrome, frameshift mutations in the CHD7 gene, including c.6292C>T, c.7957C>T, c.718C>T, c.5883C>T, and c.2966G>A, have been reported." (PMID 39533558, 2024). "P variants in CHD7 (chromodomain helicase DNA-binding protein-7) are associated with CHARGE syndrome (Coloboma of the eye, Heart defects, Atresia of the choanae, Retardation of growth and development, Genital hypoplasia and Ear abnormalities)." (PMID 39308770, 2024). "Initially defined by specific clinical criteria, including coloboma, heart defects, choanal atresia, delayed growth, and ear anomalies, CHARGE syndrome’s diagnostic spectrum has broadened since the identification of CHD7." (PMID 38790272, 2024). "While a large proportion of CHARGE syndrome cases are directly linked to pathogenic variants of CHD7 gene itself, there remain a significant number of cases without causal annotation." (PMID 39418292, 2024). "Individuals F1:II.6 and F3:II.1 showed a high degree of similarity and Individual F5b:II.1 also showed a certain degree of similarity to individuals with CHD7-associated CHARGE syndrome." (PMID 38386308, 2024). "CHD8 and its paralog CHD7 have been previously linked to the CHARGE syndrome in which renal anomalies have been described." (PMID 39350038, 2024). "The CHD7 gene, associated with CHARGE syndrome, can exhibit variable phenotypes depending on the balance between maternal contributions and genetic compensation mechanisms." (PMID 39336755, 2024). "This duality raises important questions about the role of maternal genetic material in embryonic development and the phenotypic expression of CHD7 mutations, necessitating the consideration of both zygotic and maternal effects in the study of CHARGE syndrome." (PMID 39336755, 2024). "These include an 8 kb deletion in FLT4 linked to tetralogy of Fallot and a 10 kb deletion in CHD7 associated with CHARGE syndrome caused by the insertion of an Alu element." (PMID 38339013, 2024). "Mutations in the Chromodomain helicase DNA-binding protein 7 – coding gene (CHD7) cause CHARGE syndrome (CS)." (PMID 38477756, 2024). "Updates to clinical diagnostic criteria have enhanced our understanding of both major and minor features linked to CHARGE syndrome, showcasing the considerable variability in phenotypic severity reported since the identification of CHD7." (PMID 38790272, 2024). "CHARGE syndrome, characterized by a distinct set of clinical features, has been linked primarily to mutations in the CHD7 gene." (PMID 38790272, 2024). "Over 500 different pathogenic variants of CHD7 have been described, accounting for >90% of CHARGE syndrome cases." (PMID 39418292, 2024). "For example, within the Extension cohort, one patient had an intronic CHD7 c.5607 + 17A > G variant that was de novo with the patient demonstrating features consistent with CHARGE syndrome." (PMID 39402625, 2024). "Loss-of-function pathogenic variants in the CHD7 gene account for approximately 65–70% of CHARGE syndrome cases." (PMID 39285472, 2024).
CHARGE syndrome (continued). "Both proteins are important for proper neural development as heterozygous mutations in Chd7 and Chd8 are causative for CHARGE syndrome and correlated with autism spectrum disorders, respectively." (PMID 38512854, 2024). "This suggested that CHD7 enhancers lie within genomic regions already shown to be susceptible to alterations implicated in CHARGE syndrome." (PMID 39418292, 2024). "CHARGE syndrome, driven by de novo mutations in the CHD7 gene, exemplifies the intricate interplay between PTCs, maternal influence, and genetic compensation mechanisms." (PMID 39336755, 2024). "In 2004, CHD7 was identified as a gene responsible for CHARGE syndrome, with pathogenic CHD7 variants being identified in 70–90% of suspected cases." (PMID 38790272, 2024). "Variations in the CHD7 gene are linked to various developmental disorders, including CHARGE syndrome (OMIM #214800) and Kallmann syndrome." (PMID 37745857, 2023). "Variations in gene CHD7 caused the majority of CHARGE syndrome cases; however, there are only two studies that identified an association between CHARGE syndrome and JBTS, and one of these studies was by our research team." (PMID 37547106, 2023). "CHARGE syndrome was confirmed post-mortem by a heterozygous de novo pathogenic variation in the CHD7 gene (c." (PMID 37664547, 2023). "The case of CHD7 variant, which followed an autosomal dominant inheritance pattern, was diagnosed with CHARGE syndrome combined with typical JBTS manifestations of cerebellar vermis agenesis." (PMID 37547106, 2023). "Heterozygous loss-of-function mutations in the chromodomain helicase DNA-binding protein 7 (CHD7) gene cause CHARGE syndrome characterized by various congenital anomalies." (PMID 37231428, 2023). "CHARGE syndrome is an autosomal dominant disorder that most often results from de novo mutations in the CHD7 (chromodomain helicase DNA binding protein 7) gene." (PMID 40041264, 2023). "CHARGE syndrome typically results from mutations in the gene encoding chromodomain helicase DNA-binding protein 7 (CHD7)." (PMID 37239446, 2023). "Haploinsufficiency of the chromo-domain protein CHD7 underlies most cases of CHARGE syndrome, a multisystem birth defect including congenital heart malformation." (PMID 37052590, 2023). "More than 500 heterozygous CHD7 mutations have been identified in CHARGE syndrome patients, most of which are nonsense, frameshift indels, splice site and missense mutations." (PMID 36831199, 2023). "Further gene panel testing was positive for pathogenic variant in CHD7 gene, consistent with CHARGE syndrome." (PMID 40041264, 2023). "Heterozygous loss-of-function mutations in the chromodomain helicase DNA-binding protein 7 (CHD7) gene constitute the major pathogenic cause of CHARGE syndrome." (PMID 37231428, 2023). "CHARGE syndrome is a neural crest-related disorder mainly caused by mutation of the chromatin remodeler-coding gene CHD7." (PMID 37221016, 2023). "Intellectual disability has also been related to mutations in gene CHD7, responsible for CHARGE syndrome (coloboma, heart anomalies, choanal atresia, intellectual disability, genital/urinary defects, and hearing loss)." (PMID 35199317, 2022). "While both Chd7+/tm2a and Chd7+/Whi heterozygous LoF affect multiple organs, recapitulating core features of CHARGE syndrome, the inbred genetic background of Chd7Whi line associates with the most severe phenotypes, sometimes having reduced penetrance." (PMID 36232804, 2022). "This study collected typical patients with CHARGE syndrome in Southern China, identified five novel mutation sites, expanded the mutation spectrum of the CHD7 gene and the phenotype of CS, and provided guidance for clinical diagnosis and genetic counseling." (PMID 35938004, 2022). "CHARGE syndrome is a rare congenital disorder frequently caused by mutations in the chromodomain helicase DNA-binding protein-7 CHD7." (PMID 36232804, 2022).
CHARGE syndrome (continued). "Mutations in the gene encoding Chromodomain helicase DNA binding protein 7 (CHD7) cause the majority of CHARGE syndrome cases." (PMID 36172288, 2022). "The expansion of the phenotypes described can be partially attributed to the identification in 2004 of the major causative gene, CHD7, which is reported to be mutant in 70%–90% of CHARGE syndrome cases." (PMID 36172288, 2022). "Since identification of CHD7 as a causative gene in CHARGE syndrome, research has focused on understanding its role in the affected tissues." (PMID 36172288, 2022). "For CHD7 variants, the rare sequencing variants (RSVs) of P or LP showed commonly associated with CHARGE syndrome." (PMID 36245975, 2022). "Previously, we described two novel partners, XPO4, which is involved in nucleo-cytoplasmic trafficking, and CHD7, a chromatin remodeling ATPase associated with CHARGE syndrome." (PMID 35615634, 2022). "Congenital heart defects occur in almost 80% of patients with CHARGE syndrome, a sporadically occurring disease causing craniofacial and other abnormalities due to mutations in the CHD7 gene." (PMID 36568983, 2022). "De novo mutations in CHD7 are the major cause of CHARGE syndrome which features multiple developmental defects." (PMID 34663690, 2022). "Mutations in CHD7 cause CHARGE syndrome, affecting multiple organs including the inner ear in humans." (PMID 36396635, 2022). "Previously, we showed that CHD7, which is linked to CHARGE syndrome, directly interacts with SOX2, which in turn is linked to AEG syndrome." (PMID 35615634, 2022). "One possible explanation is that loss of CHD7 results in additional retinal abnormalities that are currently underdiagnosed in CHARGE syndrome." (PMID 36172288, 2022). "Mutations in the chromatin remodeler CHD7 cause CHARGE syndrome, affecting development of several organs including the inner ear." (PMID 36396635, 2022). "Heterogeneous Chd7-mutated mice exhibit many features of CHARGE syndrome, such as craniofacial tissues and defects of the ear and heart." (PMID 36032672, 2022). "Variants of loss of function in CHD7 are associated with CHARGE syndrome (OMIM# 214800), a combination of multiple congenital malformations in which 70–92% of cases have cardiac defects." (PMID 36011280, 2022). "All 4 CHD7 mutations in fetuses were truncating variants, which validated the prior data of typical CHARGE syndrome caused by CHD7 variants." (PMID 34980134, 2022). "The wide spectrum of phenotypes that have now been described for individuals with CHD7-associated CHARGE syndrome has resulted in several different published clinical diagnostic criteria centered on major and minor characteristics." (PMID 36172288, 2022). "The majority of CHARGE syndrome cases are caused by heterozygous mutations in CHD7 on chromosome 8q21." (PMID 35246073, 2022). "Pathogenic variants of CHD7 are known to be associated with CHARGE syndrome [MIM: 214800] and hypogonadotropic hypogonadism with or without anosmia [MIM: 612370]." (PMID 34837038, 2022). "As previously reported, CHARGE syndrome is mainly caused by the CHD7 mutation in neural crest stem cells, while patients with CHD7 mutations in MSCs have not been studied." (PMID 35418650, 2022). "Mutations of the Chd7 gene are considered to be drivers of CHARGE syndrome in humans, which causes several common developmental disorders including coloboma, heart defects, atresia choanae, growth retardation, genital abnormalities, and ear abnormalities." (PMID 34663690, 2022). "One of the shared down-regulated genes is CHD7, which is frequently associated with CHARGE syndrome and has been shown to be highly relevant for neuronal differentiation and brain development." (PMID 35931711, 2022). "Although CHD7 was originally considered to be the causative gene for CHARGE syndrome, subsequent research showed that CHD7 mutations can also be detected in KS patients lacking mutations in KAL1, FGFR1, PROK2, and PROKR2." (PMID 34231173, 2022).